SULT1C2 (sulfotransferase family 1C member 2)
Description:
Sulfotransferase that utilizes 3'-phospho-5'-adenylyl sulfate (PAPS) to catalyze the sulfate conjugation of phenolic compounds. Does not transfer sulfate to steroids, dopamine, acetaminophen, or alpha-naphthol. Except in mitochondria, where it can add sulfate to cholesterol producing cholesterol sulfate, which alters mitochondrial membrane organization, and impacts protein complex mobility increasing state-III respiration, thereby modulating mitochondrial respiration (By similarity). Catalyzes the sulfation of the carcinogenic N-hydroxy-2-acetylaminofluorene leading to highly reactive intermediates capable of forming DNA adducts, potentially resulting in mutagenesis.
Synonyms: ST1C2; SULT1C1; ST1C1; humSULTC2
Tractability: Small molecule: a structure with a bound ligand is known; it has a high-quality binding pocket.
Target class: Enzyme; Transferase
Gene: Protein-coding gene on chromosome 2 (108,288,639 to 108,309,915, forward strand). Ensembl gene ENSG00000198203.
Subcellular location: Cytoplasm; Lysosome; Mitochondrion
Pathways (Reactome):
Metabolism: Cytosolic sulfonation of small molecules
Gene Ontology:
Molecular function: aryl sulfotransferase activity; protein binding; sulfotransferase activity; cholesterol sulfotransferase activity
Biological process: sulfation; amine metabolic process; sulfur compound metabolic process
Cellular component: cytoplasm; cytosol; lysosome; mitochondrion
Genetic constraint (gnomAD): Loss-of-function variants: 29 observed, 39.67 expected, observed/expected ratio (o/e) 0.73, 90% interval 0.54 to 1. The upper end of that interval is the gene's LOEUF score, 1, which puts it in group 4 of 6, group 1 being the genes least tolerant of losing a copy. Missense variants: 395 observed, 377.45 expected, observed/expected ratio (o/e) 1.05, 90% interval 0.96 to 1.14. Synonymous variants: 121 observed, 122.68 expected, observed/expected ratio (o/e) 0.99, 90% interval 0.85 to 1.15.
Homologues: Orthologues: chimpanzee SULT1C2 (93% identical), macaque SULT1C2 (92% identical), dog SULT1C2 (87% identical), rabbit SULT1C2 (85% identical), rat LOC120094625 (84% identical), rat Sult1c2 (84% identical), mouse Sult1c2 (83% identical), rat Sult1c2al1 (81% identical), guinea pig SULT1C2 (80% identical), rat Sult1c2a (80% identical), pig SULT1C2 (78% identical), rat Sult1c2al1 (78% identical), and 4 more. Paralogues in human: SULT1C4 (62% identical), SULT1C3 (53% identical), SULT1B1 (52% identical), SULT1A1 (51% identical), SULT1A2 (51% identical), SULT1A3 (50% identical), SULT1A4 (50% identical), SULT1E1 (47% identical), SULT2A1 (36% identical), SULT2B1 (34% identical), SULT4A1 (31% identical), SULT6B1 (29% identical).
Diseases named in the same sentence as SULT1C2 in open-access papers:
SULT1C2 is named in the same sentence as 16 diseases in open-access papers, as found by Europe PMC text mining. Sharing a sentence is not in itself a finding about the gene and the disease. The quoted sentences say what the papers report.
hepatocellular carcinoma (3 papers, 2023 to 2025). A malignant tumor that arises from hepatocytes. "For example, the overexpression of SULT1C2 has been associated with the growth, survival, migration, and invasiveness of hepatocellular carcinoma cells." (PMID 37835382, 2023).
glioblastoma (1 paper, 2023). The most malignant astrocytic tumor (WHO grade IV). "Although the SULT1C2 expression patterns in human prostate cancer and glioblastoma require further investigations, findings from our laboratory support the development of SULT1C2 inhibitors to treat HCC." (PMID 36880364, 2023).
lipid metabolism disorder (1 paper, 2022). "SULT1C2 plays an important role in toxin clearance and lipid metabolism disorder, and these genes are highly expressed in 3.5-year-old Tibetan sheep, indicating that Tibetan sheep have the highest immune, digestive and metabolic functions in the adult stage." (PMID 36555715, 2022).
lung adenocarcinoma (1 paper, 2021). A carcinoma that arises from the lung and is characterized by the presence of malignant glandular epithelial cells. "To determine if SULT1C2 contributes to tobacco-related carcinogenesis in the lung, we analyzed the expression and epigenetic state of SULT1C2 in human lung adenocarcinoma (LUAD) samples and in LUAD cell lines exposed to cigarette smoke condensate (CSC)." (PMID 35010676, 2021). "Our analyses indicate a complex role for SULT1C2 in lung adenocarcinoma." (PMID 35010676, 2021). "We selected three cell lines with varying levels of SULT1C2 endogenous expression: immortalized non-cancerous lung epithelial cell line BEAS-2B and two lung adenocarcinoma cell lines, H2347 and PC3_LUAD." (PMID 35010676, 2021).
Obesity (1 paper, 2021). Accumulation of substantial excess body fat. "SULT1C2 and UBD (ubiquitin D) were responsible for progression of kidney diseases, but these genes might be liable for advancement of obesity associated type 2 diabetes mellitus." (PMID 33902539, 2021).
PEComas (1 paper, 2025). "PEComas are also characterized by specific transcriptomic features of the overexpressed DAPL1, MLANA, SULT1C2, GPR143 and CHI3L1 genes, as well as epigenetic features of lysosomal and melanocyte proteins as biomarkers." (PMID 40989692, 2025).
prostate carcinoma (1 paper, 2023). A carcinoma that arises from epithelial cells of the prostate gland. "Interestingly, one study showed that the polymorphism of SULT1C2 was associated with the response to anti‐cancer drugs in prostate cancer patients." (PMID 36880364, 2023).
cancer (4 papers, 2020 to 2026). A tumor composed of atypical neoplastic, often pleomorphic cells that invade other tissues. "Although the physiological substrates of SULT1C2 remain unknown, sulfation and de‐sulfation have been shown to regulate cancer progression." (PMID 36880364, 2023). "However, currently identified SULT1C2 substrates did not explain the pro‐cancer effect, and the physiological substrates remain unknown." (PMID 36880364, 2023).
tumor (4 papers, 2021 to 2024). "Consistent with the in vitro finding, our data showed that SULT1C2 knockdown led to increased apoptosis in the Huh7‐inoculated tumor tissues." (PMID 36880364, 2023). "Our data showed that SULT1C2 knockdown Huh7 cells' tumor sizes were significantly smaller than the controls." (PMID 36880364, 2023). "SULT1C2 expression is elevated in adjacent non-tumor lung of Asians relative to Caucasians and is significantly correlated to SULT1C2 promoter methylation levels." (PMID 35010676, 2021). "To test this, we utilized RNA expression levels of AHR and SULT1C2 generated by the TCGA PanCancer study through the Tumor-Immune Estimation Resource (TIMER2.0) portal." (PMID 35010676, 2021). "Third, we discovered that race can play a significant role in levels of DNA methylation at the SULT1C2 promoter as well as overall expression of the SULT1C2 gene in non-tumor lung tissue." (PMID 35010676, 2021). "In Yap1KD; Gp130FF tumor organoids, we found reduced transcript levels for Igsf9 (marker for cell proliferation), Cyp2c65, (lipid and glucose metabolism), Ptgr1 and Sult1c2 (metabolite biosynthesis), and Clca1 (mucosal defence) when compared with Yap1WT; Gp130FF tumor." (PMID 37957015, 2024). "To further determine the effects of SULT1C2 knockdown on HCC apoptosis, we used TUNEL assay to analyze the apoptosis of Huh7‐inoculated tumor tissues." (PMID 36880364, 2023). "To further characterize the relationship between SULT1C2 and LUAD, we analyzed publicly available data from The Cancer Genome Atlas (TCGA) for LUAD expression in tumor and unmatched adjacent tumor normal (AdjNTL)." (PMID 35010676, 2021). "SULT1C2 expression was significantly positively correlated to overall LUAD patient survival in smokers, was elevated in LUAD tumors compared to adjacent non-tumor lung, and was significantly correlated with levels of patient exposure to tobacco smoke." (PMID 35010676, 2021).
SULT1C2 also shares sentences with these, for which no sentence is quoted: Anxiety (1 paper); bladder cancer (1); kidney diseases (1); liver cancer (1); neurological disease (1); Tremor (1); type 2 diabetes mellitus (1).